GZMB (granzyme B)
Diseases named in the same sentence as GZMB in open-access papers (continued):
Sharing a sentence is not in itself a finding about the gene and the disease.
tumor (continued). "Compartment analysis showed that at immune-tumor boundaries from NR, PD-L1 level on tumor cells is significantly higher than remote regions; however, Granzyme B expression shows the opposite pattern." (PMID 35634309, 2022). "Next, MC38 tumor–bearing mice were pretreated with an anti–PD-1 antibody to induce the release of granzyme B in the tumors upon T cell activation." (PMID 35788116, 2022). "Tumor infiltration of granzyme B+CD8+ TILs and an interferon-γ (IFN-γ) signature also denote favorable outcomes in patients with TNBC." (PMID 35132960, 2022). "The immunofluorescence staining images revealed that the expression of CD8, IFN-γ, and Granzyme B in tumor tissues of mice after free drug and SPIND2 injection without US irradiation was similar or slightly higher than those in the control group." (PMID 35821238, 2022). "First, CAR T cells eliminate tumor cells via direct cytotoxicity, which can be tested by the capability to degranulate (expression of CD107a), to produce cytotoxic molecules (i.e., granzyme B and perforin), and to induce cell death in target/tumor cells." (PMID 35328572, 2022). "We found that the overall numbers of CD8+ T cells and tumor-reactive CD8+ T cells expressing granzyme B were significantly higher in the combination treatment group than in the other treatment groups." (PMID 35104240, 2022). "Given the insufficient capacity of 18F-FDG PET to assess tumor response during the early stages of immunotherapy, we sought to develop radiotracers targeting granzyme B that were secreted by effector CD8+ cytotoxic T lymphocytes (CTLs) during immunotherapy." (PMID 35788116, 2022). "Blockade of TGF-β2 combined with PD-1 inhibition also resulted in downregulating the ratio of regulatory T cells to CTLs in the peripheral blood and tumor, resulting in increased granzyme B expression." (PMID 36358638, 2022). "Tumor samples from 16 out of 27 patients (59.3%) older than 40 years of age were highly infiltrated with granzyme B+ cells, while a low number of granzyme B+ cells was present in samples of 65.6% (61/93) of patients younger than 40 years of age (p = 0.020)." (PMID 35327381, 2022). "Our previous results show that API increases IFN-γ production from intratumoral CD8+ T cells as well as perforin and granzyme B and that this contributed to low tumor burden in PC-bearing mice." (PMID 35892872, 2022). "We also observed increased Granzyme B expression in the tumor microenvironment of BRB-E-administered tumor-bearing mice, indicating greater potential cytotoxic activity following BRB-E administration." (PMID 36016924, 2022). "Granzyme B and perforin are important cytotoxic constituents of natural killer cells and cytotoxic T lymphocyte cells to mediate apoptosis in tumour cells." (PMID 35194944, 2022). "Similar changes were also observed in analyzing granzyme B and Ki-67 expression by tumor infiltrating and splenic CD8+ and CD4+ T cells except Ki-67 expression in splenic CD4+ T cells." (PMID 35514996, 2022). "The IFN-γ release, granzyme B level, and proliferation ability significantly increased when stimulated by NK-cell-sensitive K562 tumor cells." (PMID 35783158, 2022). "Tumor specimens were obtained from one patient and revealed increased infiltration of granzyme B-expressing CTLs after vaccination." (PMID 36139542, 2022). "Further immunohistochemistry staining results confirmed that tsAb was able to efficiently redirect T cells to infiltrate tumor area and trigger T-cell signalling and cytotoxic granzyme B expression." (PMID 36451856, 2022). "The effect of GRP-R mAb-1 mediated ADCC was examined by performing immunohistochemical staining of granzyme B in the tumor tissue sections using anti-Granzyme B antibody." (PMID 36525420, 2022). "CD4+ T cells can target tumor cells in various ways, either directly by eliminating tumor cells through cytolytic mechanisms (perforin/granzyme B-dependent manner) or indirectly by modulating the TME." (PMID 35205742, 2022).
tumor (continued). "Few NK cells expressed Granzyme B overall (median 0.00 cells per mm2 in tumor and stroma), although a subset of five tumors were identified that expressed >2 Granzyme B+ NK cells per mm2." (PMID 36338744, 2022). "NK cells are activated by Fas ligand-Fas, secrete granzyme B and perforin, and induce tumor cell apoptosis, eventually inducing tumor cell necrosis by ADCC through antibody-FcR complex." (PMID 36293435, 2022). "Tumour accumulation correlated with granzyme B expression in syngeneic mice treated with cancer immunotherapy." (PMID 36297474, 2022). "Cleavage of gasdermin E by granzyme B is a potent mechanism by which cytotoxic lymphocytes can kill cancer cells and control tumour growth." (PMID 35401556, 2022). "Granzyme B produced from secretory granules by CTLs within tumor tissues is an important mediator of CD8+ T-cell effector function." (PMID 36923305, 2022). "A consistent trend was also observed when analysed on CD4+ T and CD8+ T cells separately, where Treg markers and exhaustion markers were found to be enriched in S2 tumours respectively; while the proinflammatory gene GZMB was depleted in S2 tumours." (PMID 35301339, 2022). "T-cell activation and subsequent T cell–mediated tumor cell kill can occur via two distinct pathways: the perforin-granzyme B pathway and the death receptor pathway." (PMID 36271507, 2022). "Previous studies have shown that CD8+ T cells and NK cells can recognize and remove tumour cells by secreting granzyme B." (PMID 35971127, 2022). "In particular, to assess the translational potential, tumor biopsies from patients subjected to immunotherapy were used to establish syngeneic colon cancer models to target granzyme B expression using a peptide-based probe ([68Ga]Ga-NOTA-GZP)." (PMID 35099641, 2022). "Cytotoxic T lymphocytes (CTL) and natural killer (NK) cells utilize Granzyme B (GzmB) and Perforin (Prf-1) molecules in cytotoxic granules to kill virally infected cells and tumor cells." (PMID 35326588, 2022). "The detection of cytotoxic granzyme B in only the tumor tissues treated with both GRP-R mAb and NK cells indicated that GRP-R mAb induced ADCC in tumors, consistent with our in vitro results." (PMID 36525420, 2022). "Although serpin B9 has primarily been described as an inhibitor of lymphocyte-derived granzyme B, it has also been shown to have a broader role in mediating tumour immune escape." (PMID 35401556, 2022). "Being a serine protease and pro-inflammatory factor, GZMB can affect the tumor microenvironment (TME) and promote cancer progression." (PMID 36497244, 2022). "Compared with each monotherapy, the combined treatment further increased the number of tumor-infiltrating CMVp-CTLs and potentiated the cytotoxic effector function, as evidenced by expression analysis of granzyme B." (PMID 35459256, 2022). "Since activated CTLs secrete granzyme B to induce a cytotoxic effect on tumor cells, we also examined the expression levels of granzyme B in the xenografted tumor by IHC." (PMID 36358638, 2022). "Next, we explored the effects of triple therapy on TIME and found that triple therapy increased the levels of GzmB in spleen and PB, whereas the addition of C-176 to triple therapy decreased its content in tumor." (PMID 36443299, 2022). "The cytotoxic effects of mAb-1 were confirmed with the secretion of cytotoxic granzyme B from NK cells and the reduction of mitotic tumor cells in vivo using a murine tumor xenograft model." (PMID 36525420, 2022). "This probe showed to be able to distinguish between responders and non-responders during therapy, with a correlation between PET signals and granzyme B expression in tumor samples." (PMID 35099641, 2022). "Low expression of GZMB has been related to the presence of metastases, which suggests its anti-tumour activity." (PMID 35563668, 2022).
tumor (continued). "The CD8+ cells, a kind of cytotoxic cells, can recognize tumor cells that express MHC class I molecules presented by antigen-presenting cells and produce IFN-γ, perforin, and granzyme B for targeting and killing tumor cells." (PMID 36051923, 2022). "Levels of granzyme B using IHC detection in 4T1-IseS vs 4T1 tumor pair and BT474-IdeS vs BT474 tumor pair showed significant reductions in scIgG containing (+IdeS) tumors than that in their counterpart control tumors." (PMID 36104515, 2022). "Conversely, pDCs also play the anti-tumor role by producing type I interferons (IFN-Is), which enhances the cytotoxicity of T cells and NK cells, or releasing Granzyme B that kills tumor cells directly." (PMID 36246629, 2022). "Overall, these findings support the possible biological implication of our results showing increased Ki-67 and granzyme B expression by tumor infiltrating CD4+ and CD8+ T cells in mice treated with a combination of AHCC® and DICB therapy." (PMID 35514996, 2022). "In tumor microenvironment, CD47 impairs the recruitment of NK cells, whereas treatment with anti-CD47 antibody increases NK cells killing against tumor cells by enhancing expression of granzyme B and IFN-γ." (PMID 36081498, 2022). "Our classical understanding of GzmB is that it is needed to suppress tumor activity; however, some studies have shown something different." (PMID 35326588, 2022). "CD4+ T cells exhibit developmental plasticity and can directly kill tumor cells, but they eliminate tumor cells at the slower rate and release the lower levels of Granzyme B than CD8+ T cells." (PMID 35757715, 2022). "With the capability of identifying specific T cells necessary for effective tumor immunotherapy through measuring the activity of granzyme B, a microfluidic platform has shown the potential in evaluating the sensitivity of immunotherapy." (PMID 36159996, 2022). "As a result of that enhanced expression of IFN-γ and GZMB in the tumor microenvironment can achieve optimal tumor clearance." (PMID 35399535, 2022). "Human and mouse basophils release granzyme B, that reportedly exerts cytotoxic effects on tumor cells." (PMID 36578500, 2022). "T cell effector function in immunotherapy relies on the release of perforin and granzyme B, which enter tumor cells and trigger the caspase cascade, leading to tumor cell death." (PMID 35788116, 2022). "Since we observed BRB-E-mediated modulation of cytotoxic T cells in the tumor microenvironment, we next explored Granzyme B production among CD8+ T cells within the spleen and draining lymph nodes of these mice." (PMID 36016924, 2022). "Mice lacking TβRII specifically in T cells display enhanced Th1 responses and strengthened anti-tumor phenotypes, such as production of GZMB and IFN-γ61–65." (PMID 35915084, 2022). "IHC examination of the tumours indicated that FU/Oxa treatment significantly elevated caspase‐3 cleavage and granzyme B expression in CT26‐SA14 allograft tumours." (PMID 35858011, 2022). "This led to pronounced CTL dysfunction as marked by a decrease in tumor infiltration, cytokine and granzyme B production, and tumor control." (PMID 35039633, 2022). "Tumor tissue from mice that received injected αOX40 was denser, showed proliferation markers, and some granzyme B, suggesting the presence of cytotoxicity or NK cells although T cells were not overtly observed." (PMID 36611875, 2022). "Specifically, we observed that the authority score of key genes in tumor recognition, such as GZMB, NOSIP and multiple HLA family genes, were significantly incremented in D12." (PMID 35414121, 2022). "Despite these indirect functions, CD4+ T cells can eliminate tumor cells directly through the release of granzyme B and perforin and through the induction of apoptosis via FAS-FAS ligand." (PMID 35326515, 2022). "IFN-γ appears to play a dual role in the tumor microenvironment, synergistic with granzyme B-mediating tumor killing of toxic T cells." (PMID 36686771, 2022).
tumor (continued). "GSDME directly induces tumor cell pyroptosis through Caspase-3 and indirectly acts on T lymphocytes through Granzyme B, acting as a tumor suppressor gene." (PMID 35992142, 2022). "When ATVs reach the tumor site, they are activated by tumor cells, which in turn release perforin, Granzyme B, and calcium ions, eventually killing the tumor cells." (PMID 36359744, 2022). "In contrast, MC38 tumors were enriched in CD49a+ Eomes+ cells expressing high levels of GzmB, closely resembling the ILC1l subset described in the PyMT tumor model." (PMID 36372017, 2022). "In a mouse model of mammary tumors, tumor-infiltrating ILC1s producing high levels of granzyme B lysed tumor cells directly." (PMID 35962192, 2022). "For instance, in a mouse melanoma model HIF-1α-/- CD8+ T cells show decreased expression of soluble factors including TNFα, IFNγ and granzyme B and tumor infiltration under hypoxia correlating with increased tumor growth." (PMID 35769460, 2022). "Separate studies published the same year discovered that CD8+ T cells and NK cells both induce pyroptosis in tumor cells via granzyme B (an enzyme capable of cleaving GSDME)." (PMID 35677632, 2022). "Granzyme B is reversible with respect to the anti-tumor cytotoxic effect exerted by HDAC inhibitors." (PMID 35163049, 2022). "We also noted that high granzyme B levels were still present in tumor tissues after 90Y-GZP as measured by immunofluorescence in both tumor models, but lower levels of granzyme B were found in CT26 tumor-bearing mice as measured by Western blot (WB)." (PMID 35890355, 2022). "CD8+ cytotoxic T cells can attenuate tumor growth by expressing FasL and secreting granzyme B and IFN-γ." (PMID 36248873, 2022). "Meanwhile, the prognostic gene model of CRC found that the higher the expression level of GZMB, the longer the OS of patients, suggesting that GZMB functioned as a promising tumor suppressor in CRC." (PMID 35464869, 2022). "Consistently, flow cytometric analysis revealed that the overall numbers of CD8+ T cells and tumor-reactive CD8+ T cells expressing granzyme B and the percentage of apoptotic tumor cells were significantly lower in the CT26 P3 cells than in the CT26 P0 cells." (PMID 35104240, 2022). "While platelets clearly inhibited cytolytic release of activated CD8+ T cells, except for Granzyme B, tumour cell-induced platelet releasates further enhanced the activation with CD3/CD28/CD2 stimulating antibodies." (PMID 35285006, 2022). "Repeated vaccination with the unmodified Neo-LNP in B16F10 tumour-bearing mice increased splenic antigen-specific granzyme B+ CD8+ T cells." (PMID 36311701, 2022). "In order to determine if the presence of tumor scIgGs impacted NK cell activation and cytotoxicity, we measured granzyme B, perforin, and natural cytotoxicity triggering receptor 1 (NCR1/NKp46/CD335) as molecular signatures of NK cell activation." (PMID 36104515, 2022). "The proportion of tumor-infiltrating NK cells expressing granzyme B and perforin were decreased and increased, respectively, in mice treated with 9D9 alone." (PMID 35239514, 2022). "Granzyme B (GrB) is a serine protease excreted through exocytosis by CTLs in order to kill tumor cells." (PMID 36551965, 2022). "To further detect the infiltration of T cells in tumor tissue, we examined the number of Granzyme B+CD8+ T cells and FOXP3+ Tregs within the tumor tissues." (PMID 36163134, 2022). "As reported, NK cells respond to tumor cells by producing cytotoxicity cytokines, including INF-γ, PRF, and GZMB which directly targeted tumor cells to exerted their functions." (PMID 36213822, 2022). "The antitumor capacity of tumor-infiltrating CD8+ T displayed similar trend as revealed by the positive percentage of granzyme B and IFN-γ in these cells in different groups." (PMID 35738798, 2022).
tumor (continued). "High levels of lactate in the TME interfere with the secretion of the antitumor cytokines INF-γ, perforin, and granzyme B in T cells and NK cells, thereby promoting tumor immune escape and growth." (PMID 36686771, 2022). "In a 2020 study, researchers found that CAT-T cells activate caspase-3/gasdermin E by activating granzyme B in tumor cells, thereby inducing tumor cell pyroptosis." (PMID 36038533, 2022). "Instead, we provide evidence that impaired autophagy leads to reduced granzyme B clearance, suggesting that Vps4b or Atg5 depletion facilitates tumor cell lysis by CD8+ T cells through enhanced granzyme B accumulation." (PMID 35379808, 2022). "At the same time, activated MAIT cells secrete granzyme B, perforin, interferon γ, and other toxic cytokines, which can mediate anti-tumor effects." (PMID 36052080, 2022). "We then detected the abundance of CD3+, CD4+, CD8+, Granzyme B+ and F4/80+ cells in the tumour by immunohistochemistry and flow cytometry." (PMID 34732697, 2021). "The survival benefit was accompanied by significant tumor infiltration by granzyme B-, IFNγ-, and TNFα-secreting effector T cells." (PMID 33503832, 2021). "For example, the presence of tumor cells expressing serine protease inhibitor-9 (PI-9), an irreversible inhibitor of GZMB, correlated with a poorer outcome in melanoma patients." (PMID 34557197, 2021). "The most important and promising predictive biomarkers are PD-L1 expression, tumor mutational burden (TMB), immune cell gene expression profiling, CD8+ cells and Granzyme B, and molecular subtyping." (PMID 34856936, 2021). "The significant increase in the CD8+, Granzyme B+ cells were additionally observed in MelanA and S91 tumours." (PMID 34732697, 2021). "Recent studies showed that pharmacologic-dose VitC potentiates PD-1 blockade, resulting in increased macrophage and CD8 T-cell tumor infiltration, increased granzyme B production, and significant tumor regression." (PMID 34899716, 2021). "CAR+ cells that express high levels of GZMB RNA or IFNγ RNA can be observed by confocal microscopy close to the residual tumor." (PMID 34155235, 2021). "GZMB represents a serine proteinase and plays a central role in killing human tumor cell lines, which can induce cell death, apoptosis." (PMID 34126969, 2021). "We also examined immunoreactivity for granzyme B, a marker of T cell activation, and detected an increase in granzyme B production in nintedanib-treated tumours compared with vehicle-treated tumours." (PMID 33299131, 2021). "Granzyme B plays a crucial role in the apoptosis of tumor cells and is secreted by many cells, including NK cells, CD8+ T-cells, and mast cells." (PMID 33987094, 2021). "The quantity of CD3+, CD4+, CD8+, Granzyme B+ and F4/80+ cells were dramatically increased at day seven after carbon ion radiation compared to the X-ray irradiated and untreated B16 tumours." (PMID 34732697, 2021). "The populations of TILs (CD4+ and CD8+) and cytotoxic TILs (CD8+granzyme B+) in primary and distant tumor tissues and spleen of SPNpro-injected mice were higher than that of SPN-1- or SPN-2-injected mice after NIR photoirradiation." (PMID 34006860, 2021). "As a major constituent involved in cytotoxic T lymphocyte (CTL)-mediated tumor cell apoptosis, the mechanism of granzyme B (GrzB)-mediated cell death has been reasonably well defined." (PMID 33750370, 2021). "LEN significantly decreased the population of tumor-associated macrophages, as well as increased the percentage of activated CD8+ T cells secreting interferon-γ+ and granzyme B." (PMID 34868952, 2021). "Unlike other activating NK cell receptors, the engagement of CD16a to IgG is sufficient for NK cells to release perforin and granzyme B, leading to tumor cell death." (PMID 33802954, 2021). "Immunohistochemical staining revealed that the infiltration of CD8 positive T cells and granzyme B secretion in recurrent tumor tissues were obviously increased compared with the primary tumor." (PMID 34903219, 2021).